ITGB5 (integrin subunit beta 5)
Description:
Integrin alpha-V/beta-5 (ITGAV:ITGB5) is a receptor for fibronectin. It recognizes the sequence R-G-D in its ligand. (Microbial infection) Integrin ITGAV:ITGB5 acts as a receptor for adenovirus type C.
Tractability: Small molecule: a structure with a bound ligand is known; a high-quality ligand is known; it belongs to a druggable protein family. Antibody: its Gene Ontology location is reachable by antibodies, with high confidence; UniProt places it where antibodies can reach, with medium confidence; UniProt predicts a signal peptide or a membrane-spanning region; the Human Protein Atlas places it where antibodies can reach. PROTAC: ubiquitination databases record sites on it; its protein half-life has been measured; a small molecule that binds it is known. Other modalities: a drug acting on it is in phase 2 or 3 trials.
Target class: Membrane receptor
Chemical probes: CYCLORGDFV, PD013054, PD081697, PD082201, PD082556, PD085403
Gene: Protein-coding gene on chromosome 3 (124,761,948 to 124,901,418, reverse strand). Ensembl gene ENSG00000082781.
Subcellular location: Cell membrane
Subcellular location (Human Protein Atlas): Mitochondria; Plasma membrane
Pathways (Reactome):
Extracellular matrix organization: ECM proteoglycans; Integrin cell surface interactions; Molecules associated with elastic fibres; Syndecan interactions
Immune System: Cross-presentation of particulate exogenous antigens (phagosomes)
Muscle contraction: Smooth Muscle Contraction
Signal Transduction: TGF-beta receptor signaling activates SMADs
Gene Ontology:
Molecular function: protein binding; integrin binding; signaling receptor binding
Biological process: cell migration; cell-matrix adhesion; endodermal cell differentiation; epithelial cell-cell adhesion; integrin-mediated signaling pathway; stress fiber assembly; transforming growth factor beta receptor signaling pathway; cell adhesion mediated by integrin; cell-cell adhesion; wound healing, spreading of epidermal cells; formation of primary germ layer
Cellular component: cell surface; extracellular exosome; focal adhesion; integrin alphav-beta5 complex; receptor complex; integrin complex; phagocytic vesicle; plasma membrane
Genetic constraint (gnomAD): Loss-of-function variants: 32 observed, 75.62 expected, observed/expected ratio (o/e) 0.42, 90% interval 0.32 to 0.57. The upper end of that interval is the gene's LOEUF score, 0.57, which puts it in group 2 of 6, group 1 being the genes least tolerant of losing a copy. Missense variants: 823 observed, 979.36 expected, observed/expected ratio (o/e) 0.84, 90% interval 0.79 to 0.89. Synonymous variants: 357 observed, 389.39 expected, observed/expected ratio (o/e) 0.92, 90% interval 0.84 to 1.
Homologues: Orthologues: chimpanzee ITGB5 (99% identical), macaque ITGB5 (99% identical), rabbit ITGB5 (93% identical), pig ITGB5 (92% identical), rat Itgb5 (92% identical), mouse Itgb5 (92% identical), dog ITGB5 (90% identical), guinea pig ITGB5 (88% identical), zebrafish itgb5 (70% identical), tropical clawed frog itgb5 (62% identical). Paralogues in human: ITGB3 (55% identical), ITGB6 (47% identical), ITGB1 (41% identical), ITGB7 (38% identical), ITGB4 (36% identical), ITGB2 (36% identical), ITGB8 (34% identical), ITGBL1 (16% identical).
Diseases named in the same sentence as ITGB5 in open-access papers:
ITGB5 is named in the same sentence as 91 diseases in open-access papers, as found by Europe PMC text mining. Sharing a sentence is not in itself a finding about the gene and the disease. The quoted sentences say what the papers report.
breast carcinoma (13 papers, 2014 to 2025). "In contrast, we were not able to find a relationship between cilengitide sensitivity and cilengitide target integrins ITGAV, ITGB3, or ITGB5, contrary to previous observations in breast cancer cell lines and glioblastoma." (PMID 39707454, 2024). "ITGB5 has been shown to contribute to tumor development in breast cancer, epithelial-mesenchymal transition and tumor potential in carcinoma cells and TAL1 is T-cell pro-oncogene with over-expression associated with development of leukemia." (PMID 30586396, 2018). "Supporting this hypothesis, depletion of ITGB3, ITGB4 and ITGB5 reduced angiogenesis and tumor growth in breast cancer." (PMID 37215577, 2023). "The tumorigenic ability of breast cancer cells would be strengthened by the ITGB5-mediated EMT." (PMID 33591944, 2021). "Thus, ITGA2 and ITGB5 can be considered as therapeutic biomarkers for the prognosis of breast cancer." (PMID 28587194, 2017). "In the myeloid compartment, metastatic breast cancer patients show enrichments of inflammatory monocytes characterised by high RORA, MYL9 and ITGB5 transcription." (PMID 40340807, 2025). "Many of these genes have known roles in cancer gene networks such as the proto-oncogenes JUN and FOS, RAP1A (RAS-related protein 1A), ITGB5, as well as BRCA2 (Breast cancer 2, early onset) and PCNA (Proliferating cell nuclear antigen)." (PMID 26448646, 2015). "Interestingly, expression of KLK5 was high in basal-like and normal-like breast cancer subtypes with a reduction in levels in luminal B. There was reduced expression in normal tissue and basal subtypes with higher expression in luminal (ER+) and Her-2 subtypes for ITGB5, EZR, COL12A1, and COL24A1." (PMID 25593998, 2014).
glioblastoma (10 papers, 2009 to 2025). The most malignant astrocytic tumor (WHO grade IV). "This differential expression indicated that ITGB5 is crucially associated with tumor aggressiveness and the invasive characteristics of high-grade glioblastomas." (PMID 41425708, 2025). "Both HOXA10-AS and ITGB5 are highly expressed in glioblastoma, and their elevated expression is associated with unfavorable patient outcomes, providing a foundation for further investigation into their roles and interactions in this aggressive tumor type." (PMID 41425708, 2025). "Significant overexpression of ITGB5 has been linked with progressive malignancies in glioblastoma, even in patients undergoing radiotherapies." (PMID 34680783, 2021). "The elevated levels of ITGB5 were associated with a more aggressive progression of the disease, underscoring its critical role in enhancing the invasiveness and metastatic potential of glioblastoma." (PMID 41425708, 2025). "Furthermore, ITGB5 has been found to be associated with immunomodulation and angiogenesis in the glioblastoma microenvironment and is required for the formation of endothelial cells into tubes." (PMID 36249018, 2022). "First, while we demonstrated that HOXA10-AS knockdown leads to decreased invasion and migration of glioblastoma cells through ITGB5-related pathways, additional pathways warrant further exploration." (PMID 41425708, 2025). "This study also found that ITGB5 is overexpressed in high-grade glioblastomas, and elevated ITGB5 expression is indicative of poor prognosis in both TCGA and CGGA patient databases." (PMID 41425708, 2025). "Second, to clarify the detailed mechanisms by which ITGB5 facilitates the pathological process of glioblastoma, more extensive research is needed." (PMID 41425708, 2025). "The study initially analyzed the TCGA database (grade II = 226 cases, grade III = 244 cases, grade IV = 150 cases) and found that ITGB5 levels were markedly higher in grade IV glioblastomas than in lower-grade glioblastomas (grades II and III)." (PMID 41425708, 2025). "The reduced tumorigenic behavior of glioblastoma cells due to HOXA10-AS knockdown can be rescued by ITGB5 overexpression or miR-99a-3p inhibitor." (PMID 41425708, 2025). "Although the immune invasion of Itgb5 in gastric cancer and glioblastoma has been well demonstrated, its role in SCI still needs further research." (PMID 36742334, 2023). "Furthermore, HOXA10-AS acts as a sponge for miR-99a-3p in glioblastoma cells through a ceRNA mechanism, leading to increased ITGB5 expression." (PMID 41425708, 2025). "Additionally, ITGB5 has been shown to correlate with the mesenchymal subtype of glioblastoma and is involved in regulating immune responses and angiogenesis processes that are essential for glioblastoma cell migration and invasion." (PMID 41425708, 2025). "The literature reported in glioblastoma, hepatocellular carcinoma, and cervical cancer that ITGB5 could serve as a predictive biomarker." (PMID 33178362, 2020). "Furthermore, preclinical evaluations of therapeutic strategies targeting the HOXA10-AS/miR-99a-3p/ITGB5 axis, including antisense oligonucleotides or nanoparticle-based miRNA delivery systems, are warranted to assess their translational potential in improving glioblastoma treatment outcomes." (PMID 41425708, 2025). "Further analysis revealed that macrophages expressing high levels of NT5E are characterized by elevated expression of chemokines and chemokine receptors such as CCR5, CCR2, ITGAV/ITGB5, and CSF1R, which may play a role in the recruitment of macrophages into the glioblastoma microenvironment." (PMID 40191733, 2025).
gastric cancer (9 papers, 2007 to 2025). A primary or metastatic malignant neoplasm involving the stomach. "Of these 12 genes, 7 genes highly expressed in gastric cancer tissues were down-regulated (ITGB5, TYMS, MYB, APOC1, CBX5, PLA2G2A, KIF20A) and 5 low-expressed genes were up-regulated after vorinostat treatment (SCGB2A1, TCN1, CFD, APLP1, NQO1." (PMID 21931799, 2011). "Integrin subunit alpha 5 (ITGA5) and integrin subunit beta 5 (ITGB5) may form a heterodimer in gastric cancer that positively interacts with ACTN1 to promote proliferation, invasion, and EMT." (PMID 39228892, 2024). "Previous studies have shown that ITGB5 promotes SNX17-mediated endosomal recycling of transforming growth factor beta receptor type 2 (TGFBR2), which enhances gastric cancer metastasis." (PMID 40303303, 2025). "Expression of ITGB5, TYMS, MYB, APOC1, CBX5, PLA2G2A, and KIF20A which is up-regulated in human gastric cancer tissues, was significantly decreased by vorinostat." (PMID 21931799, 2011). "Nevertheless, the function of ITGB5 in gastric cancer is not yet fully elucidated." (PMID 33178362, 2020). "Moreover, gene expression analysis of gastric cancer identified a collection of genes (ITGB5, TYMS, MYB, APOC1, CBX5, PLA2G2A, and KIF20A) whose expression was elevated in gastric tumor tissue and downregulated more than 2-fold by vorinostat treatment in gastric cancer cell lines." (PMID 21931799, 2011).
glioma (8 papers, 2009 to 2025). A benign or malignant brain and spinal cord tumor that arises from glial cells (astrocytes, oligodendrocytes, ependymal cells). "Thus, elevated ITGB5 expression is associated with progressive malignancy in glioma and is specific to the mesenchymal subtype." (PMID 31616629, 2019). "Elevated ITGB5 expression was associated with a favorable outcome for glioma patients." (PMID 31616629, 2019). "Given the association between high ITGB5 expression and glioma grade, we speculated that ITGB5 could be a prognostic biomarker for glioma outcome." (PMID 31616629, 2019). "ITGB3 and ITGB5 have been reported to modulate apoptosis and proliferation in glioma cells, contributing to tumour progression." (PMID 41009755, 2025). "Survival analysis based on the expression of individual integrin genes or a multigene signature revealed that high levels of ITGAV, ITGB3 and ITGB5 correlate with a poor prognosis in glioma patients." (PMID 40281508, 2025). "A previous study showed that ITGB5 contributes to the migration and invasion of glioma cells in tube formation by endothelial cells." (PMID 34712273, 2021). "To this end, in the present study we examined the expression of ITGB5 in clinical glioma samples and its relationship with the outcome of glioma patients." (PMID 31616629, 2019). "ITGB5 was found to be associated with regulation of the immune response and angiogenesis in GBM, and was required for migration and invasion of glioma cells and tube formation by endothelial cells." (PMID 31616629, 2019). "ITGB5 not only influences the migration and invasion of glioma cells, but is also involved in regulating the immune response and angiogenesis in the tumor microenvironment." (PMID 31616629, 2019). "In summary, our study shows that a high expression level of ITGB5 is an indicator of progressive malignancy in glioma and predicts unfavorable outcome in GBM patients, even after radiotherapy." (PMID 31616629, 2019). "The biological function of ITGB5 in GBM was investigated by Gene Ontology, gene set enrichment, and in vitro loss-of-function experiments using glioma cells." (PMID 31616629, 2019). "In this study, we analyzed the expression of genes encoding integrin family members in glioma using CGGA and TCGA RNAseq datasets and found that ITGB5 showed the greatest difference in expression between LGG and GBM." (PMID 31616629, 2019). "To further investigate the expression profile of ITGB5 in glioma, we analyzed ITGB5 expression in different glioma grades." (PMID 31616629, 2019). "Elevated ITGB5 expression was highly correlated with glioma progression and a mesenchymal subtype and poor survival in GBM patients." (PMID 31616629, 2019). "By analyzing publicly accessible scRNA-seq data from human gliomas via the SingleCell portal, we detected the predominant expression of ITGAV, ITGB3 and ITGB5 (encoding αv, β3 and β5 integrins, respectively) in clusters of myeloid cells, pericytes and endothelial cells." (PMID 40281508, 2025). "To test this hypothesis, we examined the correlation between ITGB5 expression and the survival of glioma patients." (PMID 31616629, 2019). "Conversely, ITGB5 silencing decreased the expression of EMT markers in glioma cells." (PMID 31616629, 2019). "Furthermore, ITGB5 not only promoted the migration and invasion of glioma cells but also regulated the function of endothelial cells." (PMID 31616629, 2019). "To examine the functions of ITGB5 in GBM in greater detail, we used two ITGB5-specific siRNAs to knock down ITGB5 expression in a stable glioma cell line (LN229) and a primary glioma cell line derived from a clinical GBM specimen (PGC1228)." (PMID 31616629, 2019). "To investigate the function of ITGB5 in GBM, we performed knockdown experiments using siRNAs and found that glioma cell growth was unaffected by ITGB5 depletion, although their migration and invasion were reduced." (PMID 31616629, 2019).
glioma (continued). "Several genes (i.e. ITGB5 and PTK2) in the glioma invasiveness signaling are over-expressed for the invasion and migration of glioma cells in the CNS cell lines." (PMID 23937249, 2013). "Characterizing ITGB5 expression and how this is related to patient prognosis may be useful for the development of more effective treatment strategies for GBM and for predicting the outcome of glioma patients." (PMID 31616629, 2019). "ITGB5 levels increased with tumor grade, and western blot and immunohistochemical analyses of clinical specimens showed that ITGB5 was overexpressed in GBM as compared to non-tumor and grades II and III glioma tissue." (PMID 31616629, 2019). "In comparison with non-tumor tissue, glioma, especially GBM, have an elevated expression level of ITGB5." (PMID 31616629, 2019).
pancreatic adenocarcinoma (5 papers, 2011 to 2024). "ITGB5 is up-regulated in pancreatic adenocarcinoma, and its repression impairs angiogenesis both in vitro and in vivo." (PMID 23922972, 2013). "This set included integrin beta 5 (ITGB5), which we found to be upregulated in pancreatic adenocarcinoma." (PMID 22078386, 2011).
pancreatic cancer (5 papers, 2011 to 2025). "Previous research indicated that ITGB5 decreases pancreatic cancer sensitivity to radiotherapy by promoting DNA damage repair and activating the MEK/ERK pathway." (PMID 40384864, 2025). "We then investigated the possible mechanism by which ITGB5 induces enhanced radio-resistance in pancreatic cancer cells." (PMID 36249018, 2022). "In our study, the forced expression of ITGB5 not only apparently potentiated the proliferation, migration, and invasion of pancreatic cancer cells in vitro but also facilitated the growth of implanted pancreatic tumors in vivo." (PMID 36249018, 2022). "Collectively, these results show that ITGB5 plays an essential role in pancreatic cancer growth and survival." (PMID 36249018, 2022). "Firstly, we examined the expression of ITGB5 in three pancreatic cancer cell lines (BXPC3, PANC-1, and ASPC1) and one normal pancreatic cell line (HPDE6-C7)." (PMID 36249018, 2022). "In our study, colony formation assay manifested that ITGB5 silencing weakened the vitality of pancreatic cancer cells after irradiation, suggesting that ITGB5 overexpression enhanced innate radiation resistance in PAAD." (PMID 36249018, 2022). "We hypothesized that targeting ITGB5 could affect pancreatic cancer radiosensitivity through the DNA damage repair pathway." (PMID 36249018, 2022). "ITGB5 overexpression in pancreatic cancer cells promoted radio-resistance." (PMID 36249018, 2022). "However, the function of ITGB5 in pancreatic cancer and its effect on radiosensitivity remain to be reported." (PMID 36249018, 2022). "Thus, ITGB5 is an attractive candidate to be tested as biomarker and/or new drug target in pancreatic cancer." (PMID 22078386, 2011). "Concerning the clinical correlation, ITGB5 expression was clearly upregulated in patients with a T3&T4 stage or distant metastases compared to patients with T1&T2 stage or non-distant metastases, which highlighted the invasive and metastatic potential of ITGB5 expression in pancreatic cancer." (PMID 36249018, 2022). "To investigate the role of ITGB5 in PAAD, we established ITGB5 knockout or overexpression pancreatic cancer cell lines." (PMID 36249018, 2022). "Although previous data reported that H19 overexpression reduced ITGB3, ITGB5, and ITGA5 in bladder cancer cells and increased ITGB1 and ITGA1 in pancreatic cancer cells, the molecular mechanism by which H19 regulates integrin was not elucidated." (PMID 31426484, 2019).
cervical cancer (3 papers, 2020). A primary or metastatic malignant neoplasm involving the cervix. "After validation by quantitative RT-PCR, we discovered that diminished miR-128 in WT-HeLa or WT-CaSki cells markedly increased the expression levels of ITGA5, ITGB5, sLex, CEACAM-6, MMP9, and MMP23 in WT-HeLa and WT-CaSki cervical cancer cell clones." (PMID 33379338, 2020). "We further validated that the overexpression of miR-128 markedly decreased ITGA5, ITGB5, sLex, CEACAM-6, MMP-9, and MMP-23 in SSR-HeLa and SSR-CaSki cervical cancer cell clones." (PMID 33379338, 2020).
gastric tumor (3 papers, 2011 to 2023). "Expression of ITGB5 in gastric tumors is associated with extracellular matrix organization, focal adhesion and ECM-receptor interaction based on gene functional enrichment and KEGG pathway analysis." (PMID 37296997, 2023). "In ITGB5, the gene expression analysis identified that its expression was elevated in gastric tumor tissue." (PMID 33178362, 2020).
hepatocellular carcinoma (3 papers, 2020 to 2022). A malignant tumor that arises from hepatocytes. "ITGB5 promoted the occurrence of hepatocellular carcinoma by interacting with the β-catenin protein." (PMID 36249018, 2022). "Induced ITGB5 was found to directly interact with β-catenin, facilitating Wnt/β-catenin activity in hepatocellular carcinoma." (PMID 34262480, 2021).
hypertrophic cardiomyopathy (3 papers, 2016 to 2024). A condition in which the myocardium is hypertrophied without an obvious cause. "KEGG pathway analysis on cardiac loop genes reveals enrichments for terms, such as dilated cardiomyopathy, vasopressin-regulated water reabsorption, and hypertrophic cardiomyopathy (the genes within these terms include: Adcy6, Aqp3, Creb3l4, Des, Itgb5, Itga9, Myl2, Myl3, and Stx4a)." (PMID 30697540, 2018).